TLR4 (toll like receptor 4)
Diseases named in the same sentence as TLR4 in open-access papers (continued):
Sharing a sentence is not in itself a finding about the gene and the disease.
bacterial infection (continued). "TLR2, TLR4, and TLR5 play important roles in bacterial infection: TLR4 recognizes LPS, a major cell wall component of Gram-negative bacteria, whereas TLR2 and TLR5 recognize peptidoglycan (PGN), another bacterial wall component, and flagellin (FLG), respectively." (PMID 22367599, 2012). "In summary, reduced TLR4 expression in CKD patients may compromise their response to bacterial infections, regardless of their prior infection history." (PMID 38922137, 2024). "This could be explained by the different pathways activated by each stimulant: conA induces a strong and non-specific activation of T-cells whereas LPS mimics a bacterial infection by activating TLR-4 and TLR-2 innate receptors." (PMID 37965258, 2023). "It is without saying that molecules other than TLR4 may also be involved in mediating CGRP release during a bacterial infection, as suggested by several studies." (PMID 33318075, 2021). "Furthermore, we found that brevenal does not alter cell surface Toll-like receptor 4 (TLR4) expression, thereby maintaining the cells’ ability to respond to bacterial infection." (PMID 30897777, 2019). "However, our results do not indicate that brevenal alters TLR4 expression or the ability of macrophages to respond to bacterial infection via the expression of this receptor." (PMID 30897777, 2019). "To our surprise, we found that CCN1 can by itself induce inflammatory responses in the absence of bacterial infection through physical interaction with TLR2 and TLR4 to activate MyD88-dependent signaling." (PMID 32144270, 2020). "This sub-inflammatory state is attributed to the direct actions of opioids on CNS expressed toll-like receptor 4 (TLR4), since opioids readily cross the BBB, rather than the indirect peripheral to central immune response following bacterial infections." (PMID 25324715, 2014). "In case of chronic inflammation and bacterial infections, the cell wall component of Gram-negative bacteria LPS is bound to CD14 membrane protein necessary for activation of MC via Toll-like receptor 4 (TLR4) which initiates cytokine and chemokine production in MC." (PMID 35163137, 2022). "Bacterial infection may also account for the previously reported constitutive high expression of TLR1, TLR2, TLR4, and TLR9 but not TLR3 in SGECs from SS patients." (PMID 32208441, 2020). "Altogether, these results show that CCN1 can directly bind and activate TLR2 and TLR4 and may function as a DAMP to regulate inflammatory responses, independent of bacterial infections." (PMID 32144270, 2020). "The combined absence of both TLR2 and TLR4 resulted in significant resistance to ascending GBS infections, in contrast with mice lacking either TLR2 or TLR4 alone; this was unsurprising as these two receptors have been described to be compensatory during acute bacterial infections." (PMID 37747229, 2023).
inflammation (186 papers, 2009 to 2026). Aberrant reaction of the microcirculation characterized by movement of fluid and leukocytes from the blood into extravascular tissues. "Excessive alcohol consumption induces the release of proinflammatory cytokines by activating the TLR4/MyD88/NF-κB signaling pathway that causes liver inflammation." (PMID 36788475, 2023). "The Toll-like receptor 4 (TLR4) signaling pathway plays a key role in Dox-induced cardiac inflammation, and growing evidence reports that TLR4-induced cardiac inflammation is strongly linked to Dox-induced cardiotoxicity." (PMID 37298770, 2023). "We next measured Tlr4 protein and mRNA expression since studies from others have suggested that antagonism of this receptor can protect against lung inflammation and associated diseases." (PMID 36976210, 2023). "As an important pathogenic factor, LPS can bind to TLR4 of Kupffer cells and cause liver inflammation and liver damage." (PMID 35563234, 2022). "Clostridioides difficile Infection-induced intestinal inflammation is associated with the regulation of the gut microbiota and the activation of TLR4/NF-κB signaling." (PMID 35663882, 2022). "A growing body of evidence has implicated Kupffer cells activated by gut-derived LPS via TLR4-mediated NF-κB signaling in the pathogenesis of alcohol-induced hepatic inflammation." (PMID 36712682, 2022). "In response to allergens, activation of LPS receptor TLR4 on lung epithelial cells can stimulate CXCL8 chemokine secretion to recruit neutrophil to the lung in association with increased eosinophilic inflammation, IgE, Th2 cytokines and mucus secretion." (PMID 33195308, 2020). "Recent studies have revealed that SNPs within TLR4 is significantly associated with gastric chronic-inflammation and HP infection related mucosa lesions." (PMID 25290654, 2014). "Thus, the TLR4/NF-kB axis in CMs can also cause cardiac inflammation and myocardial damage, and the Spike protein alone is capable of activating this axis in CMs." (PMID 37112659, 2023). "Therefore, inhibition of the TLR4/NLRP3 signaling pathway is an effective therapy for the treatment of inflammation-linked diseases, such as IVDD." (PMID 35506157, 2022). "The expression of TLR4 in the kidneyis mainly located in proximal and distal tubular epithelial cells.Ischemia associated renal inflammation upregulates the expression of TLR4 mRNAand protein in the epithelium of the distal convoluted tubule, collecting duct,and loop of Henle." (PMID 39076193, 2022). "Taken together, these evidences suggest that toll-like receptor 4 activation and subsequent upregulation of IL-1RI likely play an important role in ectopic orofacial pain associated with IL-1β expression in macrophages following tooth pulp inflammation." (PMID 33081813, 2020). "To explore the association between TLR-4 and p38 signaling in mediating thrombin-dependent endothelial inflammation, we employed pharmacological inhibitors of TLR-4 and p38, and then measured their effects on each other signaling pathway activation, respectively." (PMID 31682263, 2019). "Indeed, Tlr-4 deficiency has been shown to protect from diet induced liver inflammation and injury and the present results showing increased expression of the Tlr-4 receptor indicates increased susceptibility to a second hit involving endotoxins." (PMID 23700488, 2013). "Taken together, our findings demonstrated for the first time that administration of BR could effectively attenuate colonic inflammation in mice, at least partially, via favorable regulation of anti-oxidative and anti-inflammatory status and inhibition of the TLR4-linked NF-κB signaling pathway." (PMID 29078713, 2017). "Chronic obesity-related inflammation activates the HMGB1/TLR4/NF-κB signaling cascade, while concurrent downregulation of SIRT1 further amplifies pro-inflammatory signaling." (PMID 41505418, 2026). "Lithium treatment also exacerbates kidney inflammation, characterized by excessive expression of TLR4 proteins and NF‐κB‐p65." (PMID 41019175, 2025).
inflammation (continued). "One of the suggested targets of homocysteine is toll-like receptor 4 (TLR-4), and its mutation can attenuate the effects of HHCY-mediated vascular inflammation and mitochondria-dependent cell death." (PMID 40149955, 2025). "TLP-H, EGCG, and Chlorogenic acid can also significantly alleviate intestinal dysbiosis and liver inflammation by inhibiting the activation of the TLR4/MyD88/NF-κB signaling pathway, thereby alleviating liver injury." (PMID 41154556, 2025). "TPS administration significantly reduced the expression of the TLR4/NF-κB inflammatory signaling pathway, alleviating HS-induced hepatic inflammation." (PMID 39308975, 2024). "Another ligand for TLR4, lipopolysaccharide (LPS), has also been shown to induce neutrophilic airway inflammation in OVA-induced asthmatic mice." (PMID 39061887, 2024). "Recent research has reported that air pollution agents such as particulate matter, activated TLR2- and TLR4-mediated lung inflammations, however, the mechanism of pathogenesis for lung inflammation due to microplastic exposure is still unclear." (PMID 38525136, 2024). "Previous studies have demonstrated the important role of the TLR4/MyD88/NF-κB pathway in liver inflammation." (PMID 38790731, 2024). "The results of this study are consistent to our study, in which we found that SH significantly ameliorated P. aeruginosa lung inflammation through activation of the TLR4/NF-κB signaling pathway and improved intestinal flora dysbiosis." (PMID 36530439, 2022). "YPG alleviates BA by blocking the TLR4 signaling pathway, thus inhibiting pyroptosis in the smooth muscle cells of the airway and reducing bronchial inflammation." (PMID 36091667, 2022). "Focusing on role of inflammasome, especially in brain inflammation, NF-κB/TLR4/NLRP3 inflammasome initiate signaling pathway." (PMID 36015160, 2022). "These suggested that chronic cold stress activated the TLR4/MyD88 pathway to induce lung inflammation." (PMID 36142633, 2022). "Diet-induced colonic inflammation and dysmotility were reported to involve the activation of TLR4 and iNOS signalling." (PMID 36142897, 2022). "Previous research suggested that synovial inflammation can affect the cartilage innate immune system through TLR4/MyD88 signalling pathway, induce cartilage inflammation and degeneration and then aggravate the OA process." (PMID 34964259, 2022). "PM2.5-bound LPS can also modulate splenocyte immune response and exacerbate airway inflammation by TLR4 and−2 pathways." (PMID 35909698, 2022). "Lycopene alleviated HDF-induced renal inflammation by inhibiting the TLR4/MyD88 inflammatory pathway by blocking inflammation in mice kidneys, including NF-kB, TNF-a, and IL-6." (PMID 36230117, 2022). "Studies have shown that AMPK activation suppressed de novo lipogenesis, and the HMGB1/TLR4/NF-κB pathway was involved in liver inflammation." (PMID 33959665, 2021). "LPS-induced liver inflammation has been shown to depend on TLR4 when comparing WT and TLR4−/− mice exposed to LPS and similar responses were provoked in primary hepatic Kupffer cells isolated from the mice following LPS exposure." (PMID 34717665, 2021). "A recent study showed that Toll-like receptor 4/MyD88 pathway activation was one of two major immune responses in acute lung inflammation in mice after intratracheally instillation of PM2.5." (PMID 33194559, 2020). "Bacterial lipopolysaccharides (LPSs), the prototypical class of MAMPs are sufficient to elicit mammary inflammation mediated by TLR4 signaling and activation of nuclear factor kB (NF-kB), the master regulator of inflammation." (PMID 32539761, 2020). "Collectively, our findings demonstrate that in immature mice repetitive LPS exposure, through TLR4 signaling increases lung inflammation and impairs lung alveolar growth in a CCR2-dependent manner." (PMID 33117383, 2020).
inflammation (continued). "Active DD lesions (M1 and M2 and reactivated M4.1) were characterized by acute ulcerative inflammation, increased Cxcl-8, TLR4, and β-defensin gene expression, and the presence of abundant spirochetes." (PMID 30072966, 2018). "All results demonstrated the protective effects of Baicalin pretreatment against LPS-induced liver inflammation in chicken via negative regulation of inflammatory mediators through the down-regulation of TLR4 expression and the inhibition of NF-kB activation." (PMID 28868036, 2017). "In our previous work, we found that the inhibition of Mer signaling during acute pulmonary inflammation with an anti-Mer neutralizing antibody led to hyper-responsive TLR4 activation by LPS17." (PMID 27406916, 2016). "The precise contribution of TLR4-dependent O2−/ROS increases to CNI-induced vascular inflammation was further evaluated in endothelial cells chosen as model of CNI-induced TLR4 signaling." (PMID 27295076, 2016). "To evaluate if TLR4 signaling was required for S100A8/A9-induced aggravation of VILI we analyzed pulmonary inflammation in TLR4 mutant mice." (PMID 23874727, 2013). "TLR4-mediated NF-κB signaling plays a vital role in the initiation of cerebral inflammation in several central nervous system (CNS) diseases, such as inflammatory or autoimmune CNS diseases, and cerebral ischemic injury." (PMID 22272328, 2012). "The primary objective of the present investigation was to determine the contribution of TLR2 and TLR4 in lung inflammation and injury induced by PLN in vivo." (PMID 19956717, 2009). "The primary objective of the present study was to determine the role of TLR2 and TLR4 in lung inflammation induced by intrapulmonary delivery of PLN." (PMID 19956717, 2009). "Alcohol‐induced hepatic inflammation involves a variety of complex mechanisms, the core mechanism of which lies in LPS translocation and its triggered hyperactivation of the TLR4/NF‐κB/NLRP3 inflammatory axis." (PMID 41509195, 2026). "In conclusion, IGU ameliorates BLM-induced pulmonary inflammation in mice by blocking the TLR4/NFκB pathway, suppressing macrophage activation, and preventing M1 macrophage polarization, thereby reducing PF caused by the polarization of M2 macrophages and EMT in the advanced stage." (PMID 40181990, 2025). "LPS can cross the intestinal barrier into the body circulation and reach the lungs, where it exacerbates COPD lung inflammation through the toll-like receptor 4/ nuclear transcription factor-κB (TLR4/ NF-κB) signaling pathway mediating the production of IL-1β, IL-6, IL-17 TNF-α." (PMID 40098933, 2025). "TLR4 activation leads to increased expression of inflammatory genes such as NF-κB, Myd88, and CD14, resulting in the production of inflammatory cytokines (IL-1β, IL-6, TNF-α), which cause liver inflammation and damage." (PMID 40362886, 2025). "Calprotectin, also known as S100A8/A9 is a heterodimeric complex of calcium-binding proteins that has recently emerged as a promising mediator of cardiac inflammation through the Toll-like receptor 4 (TLR-4) and receptor for advanced glycation end-products (RAGE) signaling pathway." (PMID 40948795, 2025). "Levels of eight metabolites were 2.44–3.74 times greater following treatment with QFDYGs vs. QFDYDs, although both demonstrated significant protective effects against pulmonary inflammation through TLR4 signaling pathway modulation, gut microbiota restoration, and metabolic regulation." (PMID 41311834, 2025). "Pathogen-associated molecular patterns (PAMPs) such as LPS, as well as Damage-associated molecular patterns (DAMPs) including High mobility group box 1 (HMGB1), can all activate NF-κB by acting on Toll-like receptors (TLRs), especially Toll-like receptor 4 (TLR4), leading to liver inflammation." (PMID 41154556, 2025).
inflammation (continued). "Nonetheless, the present study is a pioneering effort at illustrating that bowel inflammation in DIO mice could be ameliorated using purslane extracts through suppression of the TLR4/NF-κB signaling pathway." (PMID 39845784, 2024). "The TLR4/NLRP3 pathway is critical in the pathogenesis of ALI, causing sustained production of cellular factors such as IL‐1β and IL‐18, which ultimately leads to a massive outbreak of lung inflammation, resulting in tissue injury and even ARDS." (PMID 39139945, 2024). "For instance, Gram-negative bacteria-produced endotoxin lipopolysaccharides (LPS) and peptidoglycans can stimulate the toll-like receptor 4 (TLR4)- and NF-κB-involved inflammatory response, leading to systemic and renal inflammation, which further worsen kidney dysfunction." (PMID 38903987, 2024). "TLR2 and TLR4 have been reported to mediate ISO‐induced cardiac inflammation." (PMID 39118286, 2024). "In addition, GLC treatment increased intestinal barrier function, reduced LPS translocation, and reduced liver inflammation by inhibiting the activation of the LPS/TLR4/NF-κB pathway, thereby effectively ameliorating liver lesions in NAFLD mice." (PMID 37836761, 2023). "Understanding the role of the TLR4 signaling pathway in Dox-induced cardiac inflammation might be beneficial for developing a potential therapeutic strategy for Dox-induced cardiotoxicity." (PMID 37298770, 2023). "On the other hand, HFD could up-regulate the levels of inflammatory factors in serum, indicating HFD-induced renal inflammation, suggesting that TLR4/MyD88-activated signaling is involved in HFD-induced renal injury." (PMID 36230117, 2022). "Therefore, the current study suggests that dietary OA can inhibit the TLR4/NF-κB signaling pathway to improve the HDS stress-induced intestinal inflammation in broilers." (PMID 36372893, 2022). "This indicates that LPS-induced liver inflammation may be regulated by the TLR4 pathway, and continuous LPS induction may trigger the body’s endotoxin tolerance, which can prevent the fatal challenge of LPS." (PMID 36669023, 2022). "Taken together, our findings suggested that maternal NT supplementation alleviates LPS-induced intestinal inflammation in piglets, which may be related to the regulation of the TLR4/IκBα/NFκB pathway." (PMID 36387380, 2022). "Some non-immunogenic nucleotides with high-affinity HMGB binding may function as suppressing agents for HMGB-mediated inflammation disease by blocking TLR4 activation and macrophage cytokine release." (PMID 35992691, 2022). "Based on this evidence, we hypothesized that toll-like receptor 4 and IL-1RΙ expression is increased in the trigeminal ganglion following tooth pulp inflammation and involved in the enhancement of neuronal excitability in trigeminal ganglion." (PMID 33081813, 2020). "Overexpression of TLR-4 abrogated CTS-mediated inhibition of endothelial inflammation." (PMID 31682263, 2019). "Therefore, the CVOs are the blood-brain interface to initiate early stage of brain inflammation probably via direct interaction between LPS and TLR4." (PMID 29396567, 2018). "The reported role of TLR2 and TLR4 in intestinal I/R injury is controversial; however, majority of the studies conducted in pathological models other than those of intestinal inflammation have reported that the TLR2 and TLR4 signaling pathways induce inflammation." (PMID 30087540, 2018). "A shift from predominant TLR4-NF-κB signaling pathway to the PI3K/Akt signaling pathway may serve a protective role in myocardial inflammation." (PMID 27228349, 2016). "In summary we show that Co2+ can induce endothelial inflammation via activation of TLR4." (PMID 27835611, 2016).